SPP1 (secreted phosphoprotein 1)
Diseases named in the same sentence as SPP1 in open-access papers (continued):
Sharing a sentence is not in itself a finding about the gene and the disease.
tumor (continued). "Furthermore, SPP1+ macrophage was revealed to have an immunosuppressive function, and CD14+ monocyte was found to contribute to tumor progression and angiogenesis." (PMID 38600248, 2024). "The function of SPP1 + Macs in interactions with tumor cells in HNSCC has not been fully characterized." (PMID 39726047, 2024). "mM2-like TAMs were revealed to promote tumor progression by secretion of MIF and SPP1." (PMID 39507421, 2024). "Similar results were observed in detecting protein and secreted levels of SPP1, demonstrating that B4GALNT1 could promote the synthesis and secretion of SPP1 from tumor cells via HES4." (PMID 39616302, 2024). "In summary, these findings indicate that tumor cells with high IGF2BP2 expression recruit both M2‐like and SPP1+ macrophages, which together may contribute to an immunosuppressive microenvironment and affect treatment outcomes." (PMID 39711402, 2024). "We verified this by plotting the CTHRC1+GREM1+ myCAF, SPP1+APOE+ TAM, and EMT signatures from previous parts of our study, which showed clear overlays, supporting the co-localization of fibroblasts and macrophages while promoting the pro-tumor TME." (PMID 39075108, 2024). "For SPP1+ macrophages, SPP1-CD44 inhibits T-cell activation and promotes tumor immune evasion." (PMID 38600248, 2024). "VGX-1027, a compound that targets macrophages to reduce the production of TNF-α and IL-1β, was also used to verify whether SPP1 + Mac-derived TNF-α and IL-1β act on tumor cells." (PMID 39726047, 2024). "Furthermore, SPP1+ Mφ, cycling Mφ, and DCs exhibited significantly higher content in tumors, while C1QA+ and VCAN+ Mφ were reduced in tumor samples in both the LIHC and LIRI HCC cohorts." (PMID 39691723, 2024). "In addition, we verified the presence of SPP1 + Macs in clinical samples and further elucidated the effect of SPP1 + Macs on HNSCC tumor cells." (PMID 39726047, 2024). "Nevertheless, the current research on SPP1 was merely carried out in tumor, and no relevant studies can be found in the cornea direction." (PMID 38971839, 2024). "In addition, compared with neighboring tissues, CTLA4+CD8+T, SPP1+ macrophages and MRC1(CD206)+ CCL18+ macrophages were also enriched in tumor tissues in the samples of colorectal cancer liver metastasis." (PMID 38279145, 2024). "After treatment with VGX-1027, neither macrophages nor SPP1 + Macs promoted tumor cell growth, but when treated it solely on tumor cells, the inhibition was not significant." (PMID 39726047, 2024). "Importantly, Spp1+TAMs were most abundant in HGG (n = 836) compared with LGG (n = 233) and less abundant in the non-tumor bearing mice (n = 112)." (PMID 38515213, 2024). "SPP1+ macrophages represent a significant cell population within the tumor immune cell compartment with negative prognostic value in CRC24,25." (PMID 39030280, 2024). "We discovered that the SPP1+ macrophage was more likely to be M2-like, and the CD14+ monocyte could contribute to tumor angiogenesis." (PMID 38600248, 2024). "To address this hypothesis, we first conducted expression plots of CTHRC1, GREM1, SPP1, and APOE in the TCGA cohort, which were all significantly enriched in tumor samples versus control." (PMID 39075108, 2024). "In breast cancer, tumor-secreted SPP1 induces fibroblasts to differentiate into myofibroblasts, which subsequently facilitate epithelial-mesenchymal transition (EMT) and the metastasis of tumor cells through the secretion of CXCL12." (PMID 39529085, 2024). "Furthermore, the interaction between POSTN+ fibroblasts and SPP1+ macrophages contribute to ECM remodeling and coordinates to form a desmoplastic microenvironment by enhancing tumor cell ECM-receptor interactions, and cell-substrate junction organization." (PMID 38519500, 2024). "Finally, to examine the effect of SPP1 on overall tumor burden, we injected a mouse HCC cell lines (RIL-175) orthotopically into the livers of Spp1 KO and WT mice." (PMID 39372792, 2024).
tumor (continued). "Additionally, based on the cellular communication results, we identified some signaling pathways specific to the HAS group, such as SPP1 and TENASCIN, which contribute to tumor immune escape and tumor progression." (PMID 39267750, 2024). "Interestingly, the tumor weights and tumor volumes were significantly lower in the SPP1-KD, SPP1-OE + VGX-1027 and SPP1-OE + PDTC groups than in the SPP1-NC group." (PMID 39726047, 2024). "We co-transfected pcDNA-LINC01133 and si-SPP1 into ASPC-1 and BXPC-3 cells to see if SPP1 knockdown could reverse the tumor-promoting effect after LINC01133 over-expression." (PMID 38987572, 2024). "To finally investigate the effect of EGC-derived IL-6 on the SPP1+ TAM differentiation and tumor development in vivo, we orthotopically injected MC38 cells in the colonic mucosa of mice with a glial-specific deletion of IL-6 (SOX10CreERT2IL-6fl/fl) and their littermates (SOX10CreERT2IL-6wt/wt)." (PMID 39030280, 2024). "However, in addition to SPP1+ and C1QC+ TAM populations, tumour-infiltrating monocytes have been identified and described as other cancer-specific moTAM subsets including TREM2+ TAM and IL-1β+ TAM." (PMID 39430099, 2024). "SPP1+ and OLR1 macrophages are suppressive immune cells that promote tumour progression." (PMID 39658531, 2024). "Considering spatial distribution, E0 was observed to promote fibroblasts and endothelial cells, protecting tumour cells and impeding immune cells (especially myeloid cells) infiltration through FGF, MK, SPP1 and LAMININ pathways, and through SEMA3 pathway to enhance vascular formation." (PMID 38817863, 2024). "To further delineate the crucial target gene, we initially conducted a comparative analysis of SPP1, NDRG1, SFN and LDHA mRNA expression levels in clinical samples of HCC and adjacent non-tumor tissues, as well as various HCC cell lines and normal liver cell lines." (PMID 39066845, 2024). "SPP1 mRNA overexpression emerged as a significant candidate biomarker of chemoresistance and was positively correlated to the presence of epithelioid features (p = 0.007) and high FNCLCC histological tumor grade (p = 0.006)." (PMID 39409192, 2024). "Thus, analyses of public patient databases and clinical specimens support our animal model findings, effectively linking MMP14/SPP1 expression and TAN presence with tumor vasculature in human cancer." (PMID 38329810, 2024). "Research also reveals that SPP1 impacts the tumor microenvironment by promoting inflammatory responses, immune suppression, and regulating extracellular matrix (ECM) remodeling to support tumor growth." (PMID 38711918, 2024). "In vitro, both the overexpression of SPP1 and SPP1△1–48 had a negligible effect on the proliferation and migration of Hepa1-6 cells, which minimized the possible autocrine or paracrine effects of SPP1 on HCC tumor cells directly." (PMID 39529085, 2024). "SPP1+ macrophages also exemplified high expression of TGFB1, suggesting an increase in TGFβ signaling towards tumor cells and fibroblasts that directly contribute towards fibroblast recruitment, cell proliferation and EMT, although TGFβ1 was high across all groups." (PMID 39075108, 2024). "Hence, to verify the phagocytic ability of SPP1 + macrophages, we co-cultured THP-1 macrophages with the ESCC cell line KYSE150 in an indirect manner to obtain SPP1 + macrophages -like tumor macrophages." (PMID 39696410, 2024). "We also found that the OPN expression in SPP1-OE + PDTC showed less than the other two groups, which may indicate that PDTC inhibited the expression of OPN in tumor cells." (PMID 39726047, 2024). "The interaction pairs via SPP1, RARRES2, NECTIN3, LGALS9, and LAMB1 showed increased signaling in the autophagy-high tumor cells, while SEMA3C, PTN, ICAM1, GAS6, and CSF1 showed decreased signaling compared with those in the autophagy-low tumor cells." (PMID 36830707, 2023).
tumor (continued). "Further, we combined these data with cell-cell interaction and functional enrichment analysis which revealed that Macro-SPP1 and Fib-APSN are enriched in the tumor boundary across cancers and finally identified potential therapeutic targets in the tumor boundary." (PMID 36806082, 2023). "In addition, it further revealed that the crosstalk between SPP1+ macrophages and CAFs contributed to ECM remodeling and TIB formation, which led to reducing immune infiltration in the tumor tissue." (PMID 37007125, 2023). "In addition, we found that the expression of some NRGs had positive correlations with tumor-infiltrating immune cells, including PARVB, SPP1, and LYZ." (PMID 37716978, 2023). "Additionally, the relative expression of prognostic genes was significantly upregulated in the tumor samples compared to the normal samples in GSE84402, with the exception of SPP1." (PMID 36769187, 2023). "IL-6 responsive genes such as Il17 and Spp1 showed elevated signaling with active communication between cancer cells and immune and non-immune stromal cells in the tumor tissue upon DTX treatment." (PMID 37699010, 2023). "In addition, PLVAP + endothelial cells (Endo-PLVAP) were enriched in the tumor boundary and exhibited interactions with Macro-SPP1, Fib-APSN, and tumor cells." (PMID 36806082, 2023). "We found that SPP1 TAMs reside in hypoxic and necrotic tumor regions, and a novel subset of FOLR2 tissue resident macrophages (TRMs) supports the plasma cell tissue niche." (PMID 36711732, 2023). "In the independent validation set, we found regulatory chains with GAS6, TIMP1, SPP1, and VEGFA as ligands, which was consistent with our findings above, indicating that these regulatory relations may be ubiquitous in tumor cells and macrophages." (PMID 37189418, 2023). "Notably, both SPP1+ TAM and MDSC played a critical role in shaping the immunosuppressive tumor microenvironment." (PMID 37475874, 2023). "Furthermore, SPP1+ TAMs promote mCAF activation by secreting IL-1β or TGF-β1, which facilitates co-mediation of ECM remodeling by SPP1+ TAMs and mCAFs to form a pro-tumor fiber microenvironment that impedes lymphocyte infiltration." (PMID 37853464, 2023). "Our results suggest that the high expression levels of SPP1 and PTGFRN may be a key component in the LUAD early invasions and can lead to a more malignant tumor condition." (PMID 37427097, 2023). "Our previous research has shown that SPP1+ TAMs and APOE+CYSZ+ TAMs are involved in regulating tumor invasion phenotypes and glycolysis in lung cancer and the recruitment of T regulatory (Treg) cells and formation of an immunosuppressive TME in colorectal cancer (CRC), respectively." (PMID 38002057, 2023). "We found that the osteopontin (OPN, encoded by SPP1)-CD44 pair was significantly enriched between macrophages and fibroblasts in different tumor types but was absent in most normal tissues." (PMID 36744260, 2023). "In a cohort of 134 patients with CRC, negative correlations were found between SPP1 expression and distant metastasis, tumor invasion, tumor grade, and recurrence." (PMID 36895491, 2023). "Previous studies have shown that FAP+ CAFs and SPP1+ TAMs contribute to ECM remodeling and coordinate the formation of a prodesmoplastic microenvironment that prevents lymphocytes from infiltrating the tumor core." (PMID 37333982, 2023). "Compared with malignant and non-malignant regions, Macro-SPP1 was significantly enriched in the tumor boundary, while Macro-FOLR2 tended to be enriched in non-malignant region and Mono/DC cells tended to be enriched in the region surrounding the TLS." (PMID 36806082, 2023). "Upregulation of procancer genes (Spp1, Igf1, Plgs2, Plau, Ctsk, Areg, Hbegf, Il1a, Ilb) was found in TAM-WT compared with TAM-KO, and this aligns with the observation that CL-11 is required for tumor cell proliferation, tumor growth, and angiogenesis." (PMID 36883567, 2023).
tumor (continued). "In our study, we found that SPP1 secreted by APOC1+SPP1+ TAM cells bound to ITGF1 secreted by FAP+ CAFs cells, suggesting that these two subpopulations may promote HCC development by remodeling the tumor microenvironment." (PMID 37333982, 2023). "In addition, information flow mediated by SPP1 and CD44, regulate signaling pathways of tumor progression." (PMID 37675100, 2023). "Notably, Spp1 expression which like CD68 is especially high in mesenchymal GBM, correlates with both tumour grade and the extent of macrophage infiltration." (PMID 36555253, 2022). "SPP1 and EPO promote tumor progression in a variety of ways." (PMID 35572724, 2022). "SPP1 and PECAM1 were found significantly upregulated in tumor tissues." (PMID 36676937, 2022). "Whereas Alb-R26Met tumours are Afp, Spp1, Gpc3, and Epcam positive, as we previously documented, Myc-R26Met tumours do not express these markers (or at lower levels)." (PMID 36433941, 2022). "Therefore, in addition to functioning as a repressor of SPP1 in immune cells such as MDSCs and ILCs, IRF8 not only functions as an intrinsic tumor suppressor but also suppresses tumorigenesis and progression through repressing OPN expression in tumor cells." (PMID 36078039, 2022). "Macro-C4 was highlighted by high SPP1 expression and absent MHC II expression, which was regarded as a marker of tumor-associated macrophages (TAMs) and was involved in angiogenesis and metastasis promotion." (PMID 36138435, 2022). "Together, these findings imply that FAP+ fibroblasts and SPP1+ macrophages contribute to ECM remodeling and coordinate to form a desmoplastic microenvironment that prevents lymphocytes infiltrating the tumor core, further reducing the efficacy of PD-L1 treatment." (PMID 35365629, 2022). "Here, the authors perform single cell RNA-sequencing from 14 pairs of iCCA tumours and non-tumour liver tissues and propose S100P and SPP1 as markers for patient classification." (PMID 35347134, 2022). "Here, single cell and spatial RNA sequencing of tumour and adjacent normal tissues reveals an interaction between FAP+ fibroblasts and SPP1+ macrophages that could be disrupted as an immunotherapy strategy." (PMID 35365629, 2022). "Interestingly, after PD-L1/CTLA-4 treatment, CTSO, MMP1, SPP1, and TPX2 were significantly up-regulated in tumor cells." (PMID 36225568, 2022). "In conclusion, our study reveals that OTUD1 potentially acts as a tumor suppressor and suppresses erlotinib resistance of NSCLC through the YAP1/SOX9/SPP1 axis, suggesting that OTUD1 may serve as a target for reducing chemoresistance for NSCLC." (PMID 36182943, 2022). "The tumor and TME co-evolved in response to immunotherapy, and SPP1 may have acted as an important regulator in this co-evolution." (PMID 40636144, 2022). "Interestingly, we found that although tumor tissues with high infiltration of both FAP+ fibroblasts and SPP1+ macrophages showed high neoantigen features, they were characterized by non-silent richness and SNV neoantigens." (PMID 35365629, 2022). "Specifically, multiple signaling pathways may be activated in the tumor microenvironment of subtype A, including TNF, SPP1, MIF, ANGPL, and ANGPTL." (PMID 36199581, 2022). "SPP1 and GCNT3 were differentially expressed between LUAD or LUSC and non-tumor controls." (PMID 35399076, 2022). "SPP1 was mainly stained at cytoplasmic, and also with weak membrane staining in the tumor, while negative staining in tumor stromal, which was in consistent with HPA database." (PMID 36585688, 2022). "Patients with both high FAP+ fibroblasts and SPP1+ macrophages exhibited the shortest PFS compared with the signature combination groups, suggesting that these two cell types can synergistically promote tumor progression." (PMID 35365629, 2022). "The protein expression of MMP1, CD24, SDC1, and SPP1 was significantly correlated with tumor grade and subtype but not with tumor stage." (PMID 35037689, 2022).
tumor (continued). "In our study, we found that knocking down SPP1 reduced the proliferation, migration, and cell survival of ESCA cells, while overexpression of SPP1 increased these abilities, which is consistent with the tumor‐promoting effect of SPP1 in other tumors." (PMID 35593388, 2022). "S100P + SPP1− iCCAphl had less CD3+ T and CD56+ NK cells, but more CCL18+ macrophage infiltration than S100P-SPP1 + iCCApps, indicating its dampened anti-tumor immune response that may contribute to the higher invasive potential." (PMID 35347134, 2022). "All these results suggested that downregulation of SPP1 could impede DNA damage repair ability in human ESCA cells post‐radiation and lead to more prominent tumor apoptosis." (PMID 35593388, 2022). "Secreted phosphoprotein 1 (Spp1), also known as osteopontin (OPN), is a glycophosphoprotein expressed by various cell types, including macrophages, T-cells, osteoblasts, epithelial cells and tumour cells." (PMID 36555253, 2022). "In short, tumor-stromal remodeling genes FN1 and SPP1 were highly expressed in male-derived TAMs." (PMID 34804043, 2021). "For instance, integrin αvβ3 binding to SPP1 can promote cellular migration through the FAK, ERK1/2, and NF-κB signaling pathways and increase tumor progression and reduce apoptosis of cancer cells via phosphoinositide 3-kinase (PI3K)/Akt/mTOR and JAK2/STAT3 signaling pathways." (PMID 34977258, 2021). "SPP1 is abnormally elevated positively correlated with the severity of tumor malignancy and chemoresistance in breast cancer, non-small-cell lung cancer, prostate cancer, and liver cancer." (PMID 34977258, 2021). "SPP1, a multifunctional ECM phosphoprotein secreted by several cell types, is involved in various biological functions, including wound healing, bone calcification, immune responses and tumor progression." (PMID 34404882, 2021). "Meanwhile, SPP1 was also a potential ICI inhibitor and could not only up-regulate PD-L1 on the surface of TAMs but also decrease the anti-tumor effect of CD8+T and the activation of CD4+T cells." (PMID 34804043, 2021). "Additionally, LUAD tumor cells used in a model of pleural carcinomatosis were found to secrete the chemoattractant CCL2 and the protein osteopontin (SPP1) in order to mediate mast cells recruitment and degranulation." (PMID 33494181, 2021). "Interaction of SPP1 and its receptor CD47 further inhibits angiogenesis by antagonizing nitric oxide signaling in endothelial and vascular smooth muscle cells which, in turn, affects the tumor microenvironment." (PMID 33345281, 2021). "C1QC+ and SPP1+ TAMs gene signatures, but not M1/M2 gene signatures, can divide cervical patients into subgroups with different prognosis, tumor stage, different immune cell infiltration, and ICMs expression." (PMID 34295336, 2021). "Moreover, in the NOD/SCID mice bearing A549-Luc-CXCL13 cells, CXCL13 recruits CXCR5+ CD68+ macrophages to the TME, where macrophages produce secreted phosphoprotein 1 (SPP1) to promote cell migration and tumor progression." (PMID 34947813, 2021). "Surprisingly, Epi_HSPA1A, Epi_GSTA1, Epi_SPP1 showed two distinctive CNV states between normal and tumor tissue, according to which we divided these cells into two clusters, ductal-normal cells from normal tissues and ductal-tumor cells from tumor tissues." (PMID 35087839, 2021). "Further, A549 cells without SPP1 overexpression demonstrated lower tumor growth rate than SPP1 overexpression cells using the xenograft tumor mouse model." (PMID 33996808, 2021). "In addition, the expression of PPP1BC, PPP1CC and RAC1 was correlated with the tumor stage (P < 0.05); the expression of PPP1CC and SPP1 was correlated with age (P < 0.05); the expression of PPP1CB was correlated with gender (P < 0.05)." (PMID 33850056, 2021).